VAMP2 (vesicle associated membrane protein 2)
Diseases named in the same sentence as VAMP2 in open-access papers (continued):
Sharing a sentence is not in itself a finding about the gene and the disease.
glioma (4 papers, 2017 to 2024). A benign or malignant brain and spinal cord tumor that arises from glial cells (astrocytes, oligodendrocytes, ependymal cells). "Each glioma patient was assigned a risk score according to the following formula: risk score = (0.2433)*RAB13 + (0.4201)*LYPLA1 + (0.0013)*GAS1 + (−0.0463)*VAMP2 + (0.5165)*CNIH4 + (0.3109)*PICK1 + (−0.0864)*RAB6B + (0.0978)*GOLT1." (PMID 37062068, 2023). "In this study, we constructed a novel risk model for predicting the prognosis and immune microenvironment of glioma patients based on the expression of SNARE proteins VAMP2 and VAMP5." (PMID 38115820, 2023). "According to the Gene Expression Profile Interaction Analysis (GEPIA) online analysis, VAMP5 expression was significantly higher, while VAMP2 expression was significantly lower in gliomas than in normal samples." (PMID 38115820, 2023). "Vesicle-associated membrane protein 2 (VAMP2) and vesicle-associated membrane protein 5 (VAMP5) were identified as two SRGs affecting the prognoses of glioma patients." (PMID 38115820, 2023). "Our study confirmed that the expression levels of VAMP2 and VAMP5 genes were significantly associated with survival time, WHO classification, IDH, and co-deletion status of 1p19q in glioma patients." (PMID 38115820, 2023). "We constructed a risk model based on the expression of VAMP2 and VAMP5 in gliomas." (PMID 38115820, 2023). "QRT-PCR assay showed that VAMP2 mRNA was gradually decreased with the increase of WHO grades, and that it reached the lowest level in WHO 4 gliomas compared to normal tissues, while VAMP5 mRNA showed the opposite changes." (PMID 38115820, 2023). "We next validated the changes of VAMP2 and VAMP5 at both mRNA and protein levels in glioma specimens and cell lines stored in our institute." (PMID 38115820, 2023). "More importantly, we verified the changes of VAMP2 and VAMP5 at both mRNA and protein levels in different grades of gliomas collected from our hospital." (PMID 38115820, 2023). "Here we found that VAMP2 and VAMP5 were two key genes in the SNARE family that affected the prognosis of glioma patients." (PMID 38115820, 2023). "We then performed a multivariate Cox regression analysis, and the results showed that two SRGs (VAMP2 and VAMP5) had significant prognostic value in gliomas." (PMID 38115820, 2023). "More importantly, we verified the changes of VAMP2 and VAMP5 at both mRNA and protein levels in glioma specimens and cell lines." (PMID 38115820, 2023). "Western blot analysis showed that VAMP2 protein level was also gradually decreased with the increase of WHO grades, and that there was a significant difference in the VAMP2 protein between glioma and normal tissues, which was mainly based on WHO 4 gliomas." (PMID 38115820, 2023). "Thus, co-culture systems of neurons or immune cells with glioma cells are required to reveal the roles of VAMP2 and VAMP5 in the TME of gliomas." (PMID 38115820, 2023). "In addition, we found low expression of VAMP2 and high expression of VAMP5 in different glioma cell lines (U87, A172, LN229, U251, U373) compared to a human astrocyte line (HA1800)." (PMID 38115820, 2023). "Therefore, VAMP2 and VAMP5 may play an important role in the progression of gliomas." (PMID 38115820, 2023). "Secondly, we identified VAMP2 and VAMP5 as two key SNARE proteins affecting the prognoses of gliomas, but the lack of experimental evidences in glioma cells or models limits the interpretation of this finding." (PMID 38115820, 2023).
depression (3 papers, 2016 to 2025). "Similarly, when repeating analyses upon exclusion of late-life depression patients (n = 38), the associations of plasma VAMP2 [βs = −0.75 (95% CI −1.09 to −0.41)] and GFAP [βs = −0.35 (95% CI −0.57 to −0.12)] with SV2A PET SUVRcomp values were comparable." (PMID 40620474, 2025). "Second, our pathway analysis revealed that VAMP2 was a member of both the synaptic transmission pathway and protein-protein interaction network, suggesting an integral role that this gene plays in the molecular mechanism underlying depression." (PMID 26728011, 2016). "This study suggests that Gad2, Vamp2, and Pde2a are potentially involved in depression remission treated by Chaihu-Shugan-San." (PMID 35111057, 2021). "Our data show that Chaihu-Shugan-San treats depression potentially via influence 110 DEPs (Gad2, Vamp2, Pde2a, etc.), and neurotransmitters release and transmission cycle (e.g., GABA, glutamate, serotonin, norepinephrine, dopamine, and acetylcholine)." (PMID 35111057, 2021). "Here, we suggest that VAMP2 is a key player in the pathogenesis of depression, based on the following convergent evidence." (PMID 26728011, 2016). "This network consisted of a number of molecules previously reported to be associated with depression (according to a PubMed search), such as CYP3A5, VAMP2, CSGALNACT1, CASP8, CRHR2, PKD2, and OXT." (PMID 26728011, 2016). "In addition, FKBP4, PKD2, CSGALNACT1, and VAMP2 have been reported in relation to depression (or mood disorders)." (PMID 26728011, 2016).
migraine (3 papers, 2014 to 2025). "Furthermore, variants in SNAP25 and VAMP2 that affect their expression have been implicated in migraine." (PMID 39924344, 2025). "Recently, variants in the SNARE genes VAMP2, SNAP25 and STX1A have been studied as potential risk factors in several neurological disorders, including migraine." (PMID 37380951, 2023). "It has been reported that both VAMP1 and VAMP2 are expressed in trigeminal ganglion neurons involved in migraine." (PMID 25010769, 2014).
Obesity (3 papers, 2021 to 2022). Accumulation of substantial excess body fat. "Furthermore, consistent with this, it has been reported that low expression of the SNARE proteins STX1, SNAP25, and VAMP2 is associated with insulin secretory defects in rodents and humans with obesity and type 2 diabetes." (PMID 35804190, 2022). "Interestingly, it is plausible that miRs negatively control the expression of VAMP2 in adipocytes during obesity because its expression was markedly reduced in eAT of obese mice without significant change in its mRNA level." (PMID 36010657, 2022).
schizophrenia (3 papers, 2014 to 2020). A major psychotic disorder characterized by abnormalities in the perception or expression of reality. "The expression of VAMP-2 has been found to be altered in both schizophrenia and bipolar disorder within a combined microarray analysis of the Stanley Foundation's brain collections." (PMID 24886127, 2014). "These genes included the VAMP-2 gene, which has previously been associated with Axis-I disorders including MDD, bipolar depression, schizophrenia and with antidepressant treatment response." (PMID 24886127, 2014). "These genes included VAMP-2, a gene which has previously been associated with Axis-I disorders including MDD, bipolar depression, schizophrenia and with antidepressant treatment response." (PMID 24886127, 2014). "For example, miR-153 regulates Snap25, Vamp2, Snca, Trak2, Bsn and Pclo genes at the mRNA level; miR-137 inhibits complexin-1, Nsf and Syt1 in mouse model of schizophrenia; miR-34c targets VAMP-2 and miR-135a binds the complexin-1 and complexin-2 genes in the amygdala." (PMID 32252776, 2020).
bladder cancer (2 papers, 2019 to 2022). "In this study, we analyzedthe relative expression of the STX1A and VAMP2(SYB2) for their possible association in the progressionand metastasis of bladder cancer." (PMID 30672978, 2019). "Recently, it has been shown that VAMP2 is significantly expressed in bladder cancer and increases in a stage-dependent manner according to tumor stage." (PMID 36248974, 2022). "Little isknown about the expression pattern of VAMP2 in breast and lungcancers and also in bladder cancer." (PMID 30672978, 2019). "Therefore, we aimed to determine thedifference in expression of STX1A and VAMP2 inrelation to tumor grades and pathological stages in bladder cancer." (PMID 30672978, 2019).
botulism (2 papers, 2015 to 2017). A serious bacterial infection caused by botulinum toxin which is produced by Clostridium botulinum. "Scorpion venoms include many toxic peptides, but recently, a metalloprotease from Tityus serrulatus called antarease was reported to be capable of cleaving VAMP2, a protein involved in the neuroparalytic syndromes of tetanus and botulism." (PMID 28264432, 2017).
cognitive decline (2 papers, 2022 to 2023). "Notably, a reduction of VAMP2 expression in the hippocampus and the entorhinal cortex was found to be associated with cognitive decline and AD brains have a reduced level of VAMP2, STX1a and SNAP-25 compared to control brains." (PMID 35360211, 2022).
developmental delay (2 papers, 2021 to 2022). "Mutations in the signaling pathway of VAMP2 and AGRN impair proper signaling between the presynaptic and postsynaptic neurons, and can result in neurodevelopmental conditions known as global developmental delay (GDD)." (PMID 36176870, 2022).
insulinoma (2 papers, 2022). "This study examined the effect of collagen IV-β1-integrin on exocytotic proteins (Munc18-1, Snap25, and Vamp2) involved in insulin secretion using rat insulinoma (INS-1) cell line." (PMID 35573663, 2022). "Native SNARE complexes from insulinoma INS8332/13 lysates were isolated by incubation with anti-VAMP2 or VAMP8 antibody-coated superparamagnetic beads followed by extensive washing, then purified α-SNAP and NSF added in presence of ATP-Mg2+ or EDTA." (PMID 36316316, 2022).
lung carcinoma (2 papers, 2011 to 2014). "For example, VAMP2, the top most level-1 gene in the Lung Cancer data set, has a GMI value of 7.19, showing discriminating power which appears even stronger than WAS, the top most level-1 gene in the SRBCT data set." (PMID 21909426, 2011).
osteosarcoma (2 papers, 2025). A usually aggressive malignant bone-forming mesenchymal neoplasm, predominantly affecting adolescents and young adults. "Some studies of VAMP2 related to human bone have been reported; for example, miR-185 can inhibit the proliferation of osteosarcoma cells by targeting VAMP2." (PMID 40757880, 2025). "The mi-RNA185 can directly bind VAMP2 to inhibit its expression, thereby inhibiting proliferation, invasion and metastasis of osteosarcoma cells." (PMID 39953608, 2025). "In osteosarcoma, miR-185 provides rationale for treatment by reducing VAMP2 levels." (PMID 40757880, 2025).
pancreatic cancer (2 papers, 2019 to 2022). "We established 7-genes prognostic signature using the least absolute shrinkage and selection operator (LASSO) model and identified vesicle-associated membrane protein 2 (VAMP2) as a new energy metabolism-related prognostic biomarker for pancreatic cancer." (PMID 36248974, 2022). "The results of this study suggest that VAMP2 is an independent prognostic factor associated with energy metabolism in pancreatic cancer and may be involved in the immune response." (PMID 36248974, 2022). "The prognostic relationship between vesicle-associated membrane protein 2 (VAMP2) and pancreatic cancer patients was analyzed by OS and progression-free survival, and the prognosis was found to be significantly worse in the high-expression group." (PMID 36248974, 2022). "The results of an expression analysis of different clinical traits led us to focus on VAMP2, and a prognostic analysis confirmed that VAMP2 is an independent prognostic factor in pancreatic cancer." (PMID 36248974, 2022). "Since VAMP2, when highly expressed, was significantly enriched in immune-related pathways in pancreatic cancer, we performed an immune correlation analysis of VAMP2." (PMID 36248974, 2022). "The GSEA results suggest that it may be possible to mediate the immune response of immune cells by up-regulating the expression of VAMP2 to produce a therapeutic effect on pancreatic cancer." (PMID 36248974, 2022). "This suggests that VAMP2 downregulation may also affect pancreatic cancer progression by regulating the PPP." (PMID 36248974, 2022). "A Nomogram showed that VAMP2 was an independent prognostic factor in pancreatic cancer." (PMID 36248974, 2022). "The relationships between VAMP2 and both prognostic OS and PFS of pancreatic cancer patients were analyzed by grouping with median expression values." (PMID 36248974, 2022).
tetanus (2 papers, 2017 to 2025). A serious infectious disorder that follows wound contamination by the Gram-positive bacterium Clostridium tetani. "In fact, VAMP2 proteolysis by tetanus and by botulinum neurotoxin types B, D, F and G was long known to paralyze nerve terminals." (PMID 28264432, 2017).
type 1 diabetes (2 papers, 2021 to 2025). "VAMP2 significantly enriched 33 pathways, including allograft rejection, type I diabetes mellitus, and protein export." (PMID 40475761, 2025).
viral infections (2 papers, 2017 to 2020). "Compared to MAVS-ΔN141, these chimeric mutants MAVS-ΔN141-(Bcl-xL-TM) and MAVS-ΔN141-(VAMP-2-TM) lost their inhibitory effects on IFN production and MAVS aggregation upon virus infection, though they contain active regions for interaction with downstream effectors." (PMID 28607490, 2017). "Strikingly, Bcl-xL-TM, VAMP-2-TM or Pex13-TM could not inhibit MAVS activity in inducing IFN production following virus infection, nor was MAVS aggregation affected." (PMID 28607490, 2017). "Interestingly, we found that expression of RIG-I impaired RNF115–MAVS but not RNF115–MAVS–TM(VAMP-2) associations, indicating that RIG-I competitively engages MAVS against RNF115 on the mitochondria which might be responsible for the disassociation of RNF115 from MAVS after viral infections." (PMID 33139700, 2020).
alcohol dependence (1 paper, 2013). Physical and psychological dependence on alcohol. "Interestingly, a recent transcriptome profiling study used tissue from alcoholic human brain cortices to identify Vamp2 as a hub gene that is likely to have high functional significance in biological processes associated with alcohol dependence." (PMID 24376402, 2013).
atopic dermatitis (1 paper, 2018). "Distinct subsets of mast cell granules could be selectively regulated by the N-terminal-mimicking peptides derived from VAMP2 and VAMP8, and they effectively decreased the symptoms of atopic dermatitis in mouse models." (PMID 29696021, 2018).
cerebral toxoplasmosis (1 paper, 2021). Infections of the brain caused by the protozoan toxoplasma gondii that primarily arise in individuals with immunologic deficiency syndromes (see also aids-related opportunistic infections). "However, biological roles of Vamp2 along with Uqcrfs1 and Pkm in cerebral toxoplasmosis still need further exploration." (PMID 34367142, 2021).
colorectal cancer (1 paper, 2021). A primary or metastatic malignant neoplasm that affects the colon or rectum. "Supporting this, FEZ1 colocalizes with VAMP2 in developing hippocampal neurons and forms a separate complex with deleted in colorectal cancer (DCC) and Syntaxin-1 (Stx1), components of the Netrin-1 signaling pathway that are also involved in regulating axon and dendrite development." (PMID 33771901, 2021).
epileptic encephalopathies (1 paper, 2024).
epileptic syndrome (1 paper, 2015). "The relative preservation of EPSCs provides a plausible explanation of the epileptic syndrome, but it raises the question of whether this can be explained by a preservation of VAMP2 in a subset of boutons." (PMID 24442865, 2015).
haemorrhoid (1 paper, 2020). "However, the results showed that the expression levels of all important node genes (CLTA, CLTC, RAB3A, SNAP25, SYT1, VAMP2) on Synaptic vesicle cycle pathways from haemorrhoid patient samples were lower significantly than them from healthy tissue samples." (PMID 32620169, 2020).
hearing loss (1 paper, 2024). "The lead-induced cochlear synaptopathy is associated with changes in the abundance of many synaptosomal proteins, and the increase in the abundance of proteins encoded by genes such as Snap25 and Vamp2 has been associated with hearing loss in other studies." (PMID 39104440, 2024).
hippocampal atrophy (1 paper, 2023). "Taken together, future evaluation of the associations of CSF VAMP-2 and SNAP-25 with in vivo neural correlates (e.g. hippocampal atrophy) of declining episodic memory and other cognitive functions in AD patients as measured with structural MRI, could provide valuable information." (PMID 37898760, 2023).
Hyperglycemia (1 paper, 2011). An increased concentration of glucose in the blood. "The finding of reduced VAMP2 protein expression after three months of hyperglycemia agrees with our previous observations in this model." (PMID 21249158, 2011).
Hypertension (1 paper, 2023). The presence of chronic increased pressure in the systemic arterial system. "In our study, VAMP2 expression was increased in the kidney tissues of diabetic patients with hypertension." (PMID 36675205, 2023).
ischemic heart disease (1 paper, 2019). "SNAP25 rs36305, Stx-1A rs4717806, and rs2293489, VAMP2 26bp ins/del, Minor allele effect of association with ischemic heart disease (IHD) vs Control group (CG), calculated by regression analysis model with Shesis software." (PMID 31192914, 2019). "SNAP25 rs36305, Stx-1A rs4717806, and rs2293489, VAMP2 26bp ins/del genotypic and allelic polymorphism distribution in patients with ischemic heart disease (IHD) and in the control group (CG)." (PMID 31192914, 2019).
myopia (1 paper, 2019). "RPTOR and VAMP2 are two more genes identified in our study under insulin receptor signaling and were hypermethylated with a significant association with myopia." (PMID 30858441, 2019).
neuropathy (1 paper, 2025). A disorder affecting the nervous system that manifests with pain, tingling, numbness, and/or muscle weakness. "Therefore, exploring the specific mechanism of VAMP2’s role in RA neuropathy and investigating its potential as a therapeutic target is of great significance." (PMID 40475761, 2025).
non-small cell lung adenocarcinoma (1 paper, 2022). Type of epithelial lung cancer arising from glandular origin. "In addition, VAMP2 can act as a fusion gene and play an oncogenic role in non-small cell lung adenocarcinoma." (PMID 36248974, 2022).
osteonecrosis (1 paper, 2025). A none disease characterized by death of bone tissue due to a lack of blood supply. "For example, VAMP2 has been implicated as a keystone gene in osteonecrosis of the femoral head." (PMID 40757880, 2025).
ovarian carcinoma (1 paper, 2022). A malignant neoplasm originating from the surface ovarian epithelium. "MiR-646 currently seems involved in cell proliferation and metastasis in a variety of tumors and was reported to mediate the VAMP2 and MDM2 genes at the post-transcriptional regulation level, thereby inhibiting the activity of ovarian cancer cells." (PMID 35022405, 2022).
schistosomiasis (1 paper, 2015). An infectious disease caused by parasitic trematodes of the genus Schistosoma that colonize human blood vessels and release eggs that can cause granulomatous reactions leading to acute (swimmer's itch or acute schistosomiasis syndrome) or chronic disease. "The purpose of this study was to characterize Schistosoma japonicum vesicle-associated membrane protein 2 (SjVAMP2) and to investigate its potential as a candidate vaccine against schistosomiasis." (PMID 26641090, 2015).
toxoplasmosis (1 paper, 2021). A parasitic disease contracted by the ingestion or fetal transmission of toxoplasma gondii. "Vamp2 plays important roles in vesicular exocytosis and activity-dependent neurotransmitter release, which might suggest it is involved in neurological regulation during toxoplasmosis." (PMID 34367142, 2021).